LINC01254 (long independently transcribed non-coding RNA 1254)
Gene: Long non-coding RNA gene on chromosome 18 (10,404,764 to 10,414,515, reverse strand). Ensembl gene ENSG00000260913.
Diseases named in the same sentence as LINC01254 in open-access papers:
LINC01254 is named in the same sentence as 1 disease in open-access papers, as found by Europe PMC text mining. Sharing a sentence is not in itself a finding about the gene and the disease. The quoted sentences say what the papers report.
cancer (1 paper, 2024). A tumor composed of atypical neoplastic, often pleomorphic cells that invade other tissues. "The more cancer-specific lincRNAs are LINC00470, LINC00668, LINC00907, LINC01254, LINC01415, LINC01478, and LINC01539." (PMID 38540157, 2024).